SOST (sclerostin)
Diseases named in the same sentence as SOST in open-access papers (continued):
Sharing a sentence is not in itself a finding about the gene and the disease.
osteoporosis (continued). "For therapeutic use in humans, the anti-sclerostin antibody (romosozumab) has been developed for the treatment of osteoporosis, which decreases endogenous levels of sclerostin, allowing for osteogenesis through an improvement in osteoblast survival." (PMID 30126106, 2018). "In the near future antibodies against sclerostin will be on the market as a new therapeutic approach in treating osteoporosis." (PMID 30496210, 2018). "Sclerostin, which is encoded by the SOST gene, is important to study because it inhibits osteoblastic bone formation and is therefore a drug target for osteoporosis." (PMID 29065178, 2017). "Parathyroid hormone (PTH) is an endogenous hormone and osteoporosis therapeutic that suppresses sclerostin activity." (PMID 27759007, 2016). "In this article we review the currently available preclinical and clinical evidence supporting the use of sclerostin inhibitors in osteoporosis." (PMID 27016922, 2016). "Inhibition of the Wnt antagonist sclerostin increases bone mass in patients with osteoporosis and in preclinical animal models." (PMID 27230681, 2016). "Sclerostin antibodies are under clinical development to treat osteoporosis and metastatic bone disease." (PMID 27666393, 2016). "In this article we review the currently available preclinical and clinical evidence supporting the use of sclerostin inhibitors in the management of patients with osteoporosis." (PMID 27016922, 2016). "Neutralizing anti-sclerostin antibodies are able to restore Wnt activity and enhance bone growth thereby presenting a new osteoanabolic therapy approach for diseases such as osteoporosis." (PMID 27558933, 2016). "Together these findings suggest that treatment of patients with osteoporosis with sclerostin inhibitors will be of limited duration and will form part of a treatment strategy rather than monotherapy, particularly for patients with severe osteoporosis." (PMID 26892377, 2016). "Dickkopf‐1 (Dkk‐1) and sclerostin, two extracellular negative regulators of the Wnt/β‐catenin pathway, are considered as potential targets for bone anabolic anti‐osteoporosis therapy." (PMID 26941261, 2016). "A crystal structure analysis of AbD09097 provides the first high-resolution structural insights into a neutralizing anti-sclerostin antibody, which will certainly facilitate new approaches for therapies targeting osteoporosis." (PMID 27558933, 2016). "The recognition of the importance of the Wnt-signaling pathway in bone metabolism and studies of patients with rare skeletal disorders characterized by high bone mass identified sclerostin as target for the development of new therapeutics for osteoporosis." (PMID 27016922, 2016). "Given its pivotal role in regulating bone formation, sclerostin is a promising pharmacologic target for prevention and treatment of osteoporosis." (PMID 26494536, 2015). "Together with our study, these results provided evidence that sclerostin is an emerging therapeutic target for the prevention and treatment of osteoporosis in men and postmenopausal women." (PMID 26494536, 2015). "Secondary outcomes include serum biomarkers of SCI osteoporosis (sclerostin, P1NP and β-CTX), markers of immune function (IL-6, IL-10, FGF2, INF-γ, TNF-α), neurological function, body composition, depression and quality of life." (PMID 25563584, 2015). "Compared to other bone-related proteins, sclerostin is considered a candidate biomarker for SCI-induced osteoporosis." (PMID 25563584, 2015). "In a recent advance in drug discovery for osteoporosis using treatment targeting sclerostin, it is indicated that the osteocyte must be one of the major targets." (PMID 25652541, 2015). "Sclerostin antibody (Scl-Ab) represents a promising therapeutic approach to treat patients with osteoporosis." (PMID 28377954, 2015). "Novel agents targeting the Wnt inhibitors dickkopf-1 and sclerostin are currently under investigation for the treatment of osteoporosis and malignant bone disease." (PMID 25802521, 2015).
osteoporosis (continued). "Anti-sclerostin antibodies have also recently been developed and shown to increase bone formation and decrease bone resorption in clinical trials involving osteoporosis patients." (PMID 25779629, 2015). "A Dkk1-neutralizing antibody is in clinical trials for MM, and sclerostin-neutralizing antibodies have been developed for osteoporosis." (PMID 25757219, 2014). "Due to the biological actions of sclerostin, a monoclonal antibody was created and employed to treat osteoporosis." (PMID 24152444, 2013). "Although these properties make Sclerostin a prime target for an osteoanabolic therapy approach against osteoporosis, little is known about its molecular mechanism of action." (PMID 24312339, 2013). "A neutralizing antibody against Sclerostin is a new, upcoming therapeutic treatment for osteoporosis." (PMID 23028809, 2012). "We identified enhanced expression of 39 genes in hMSC-OP and reduced expression of 16 genes that are already described as reliable or promising candidates for osteoporosis, including susceptibility genes like LRP5, SPP1 (Osteopontin), COL1A1 and SOST." (PMID 23028809, 2012). "Direct connections between the protein and osteoporosis have already been described: serum levels of Sclerostin were found enhanced in postmenopausal women and one of the upcoming treatments for osteoporosis is the application of anti-Sclerostin-antibodies." (PMID 23028809, 2012). "Inhibitors of sclerostin are presently being developed to treat osteoporosis and fractures to increase bone density and aid healing." (PMID 22032690, 2011). "At this time, monoclonal antibody to sclerostin is being considered for early phase 2 clinical trials in postmenopausal women with osteoporosis and in fracture healing." (PMID 20981340, 2010). "This study demonstrates that serum sclerostin levels are significantly associated with sarcopenia but not with osteoporosis or vertebral fracture in postmenopausal women." (PMID 41594249, 2026). "According to our logistic regression analysis, while sclerostin was significantly associated with sarcopenia, it was not a significant predictor of osteoporosis." (PMID 41594249, 2026). "Univariate logistic regression analysis revealed that serum sclerostin was significantly associated with sarcopenia (estimate = 0.008, p = 0.045) but not osteoporosis (p = 0.257), suggesting its stronger relationship with muscle function than bone fragility." (PMID 41594249, 2026). "In summary, SOST may become an effective target for future osteoporosis drug research and development and may be a key molecule in revealing the pathogenesis of osteoporosis." (PMID 39606935, 2025). "Interestingly, SOST inhibition through monoclonal antibodies such as romosozumab, currently used in osteoporosis therapy, has been shown to enhance cognitive function and protect against stress-induced synaptic loss in a preclinical model." (PMID 41007423, 2025). "This may be related to the fact that there are factors that act in common between osteoporosis and sarcopenia, such as myokine, a cytokine secreted by muscle, and sclerostin, secreted by bone cells." (PMID 40943733, 2025). "The combination of anti-osteoporosis drugs such as sclerostin inhibiting antibodies and periodontal PTHrP may have a synergistic effect, potentiating bone growth." (PMID 40115506, 2025). "Aberrant DNA methylation, a significant epigenetic change, influences osteoporosis by regulating the expression of genes associated with bone metabolism (e.g., RUNX2, NFATc1, SOST) and modifying immune cell activities, thereby facilitating inflammatory bone loss." (PMID 41282636, 2025). "Direct inhibition of sclerostin by using aptamers suggests that bone-targeted drug therapy could be an effective approach to treating osteoporosis." (PMID 40277546, 2025). "Anti-sclerostin antibodies (romosozumab) used in osteoporosis treatment may also impact cognitive function, although this requires further investigation." (PMID 41007423, 2025).
osteoporosis (continued). "Similarly, PTH, the only approved anabolic drug for the treatment of osteoporosis together with the anti-sclerostin antibody Romosozumab, promotes bone formation, but also leads to increased bone resorption as a secondary effect." (PMID 38591777, 2024). "Plasma SOST levels were elevated in older adults, which is perhaps not surprising given the role of SOST in bone loss and the association between osteoporosis and Alzheimer’s disease." (PMID 39286983, 2024). "Therefore, the usage of anti-sclerostin monoclonal antibodies has progressively become a significant component in the management of osteoporosis." (PMID 39720253, 2024). "Notably, romosozumab, which targets the SOST gene, is now clinically utilized for osteoporosis treatment." (PMID 39439909, 2024). "Notably, the monoclonal antibodies Denosumab and Romosozumab have been developed to inhibit RANKL and sclerostin, respectively, indicating the pivotal role of these molecular targets in osteoporosis development." (PMID 39062550, 2024). "Interestingly romosozumab, which is a recently approved therapy against osteoporosis acting by inhibiting sclerostin, exhibit cardiovascular events as side effects." (PMID 38644839, 2024). "Monoclonal antibodies against SOST are now utilized as treatment for osteoporosis and may be particularly advantageous interventions for women who are disproportionately impacted by both osteoporosis and depression." (PMID 39286983, 2024). "Therefore, early exploration of sclerostin targets in diabetes patients plays a vital role in the prevention and treatment of diabetes-induced osteoporosis." (PMID 39720253, 2024). "Background/Objectives: Osteoporosis and cardiovascular disease (CVD) share common risk factors and pathophysiological mechanisms, raising concerns about the cardiovascular implications of sclerostin inhibition." (PMID 39767786, 2024). "Romosozumab is not only a promising agent for the management of osteoporosis, but is also exerts positive effects on bone involvement in multiple myeloma, where increased levels of sclerostin may contribute to the development of lytic lesion." (PMID 38634076, 2024). "Therefore, a humanized monoclonal anti-sclerostin antibody, romosozumab, which induces osteogenesis and inhibits osteoclastogenesis, has been used in osteoporosis therapy." (PMID 39768281, 2024). "The involvement of sclerostin in the pathogenesis of many skeletal disorders has been outlined in various studies, and more recently, antisclerotic antibodies have been approved for the treatment of osteoporosis." (PMID 39452922, 2024). "A total of 153 patients (68.0%) were receiving osteoporosis treatment (Bisphosphonates/Active vitamin D/Calcium/Selective estrogen receptor modulator/Anti-receptor activator of nuclear factor kappa B ligand antibody/Sclerostin antibody: 44/106/45/26/39/5)." (PMID 39436957, 2024). "Recent research has revealed that IGU improves disuse osteoporosis in mice by inhibiting sclerostin and the receptor activator of NF-κB ligand (RANKL) through the extracellular signal-regulated kinase/early growth response protein 1/TNF-α pathway in osteocytes." (PMID 39449973, 2024). "In this context, targeting sclerostin is a promising therapeutic strategy for osteoporosis." (PMID 39767786, 2024). "This in addition to the fact that PPARγ promotes sclerostin (SOST) production which is considered one of the best targets for osteoporosis and the fact that PPARγ is associated with the regulation of ROS, makes it a lucrative target for osteoporosis as well." (PMID 39707534, 2024). "Osteoblasts are responsible for bone mineralization but the abovesaid inhibitory pathway may affect the normal bone remodelling process in osteoporosis.Therefore, serum sclerostin might be a choice for diagnosis of osteoporosis." (PMID 38352898, 2024). "The researchers propose that sclerostin mediates osteoporosis in T2D by inhibiting WNT signaling." (PMID 39720253, 2024).
osteoporosis (continued). "Furthermore, its involvement in diverse pathologic conditions supports sclerostin as a therapeutic target, with an anti-sclerostin antibody recently approved in our country for the treatment of osteoporosis." (PMID 38634076, 2024). "For instance, sclerostin is known to decrease bone formation and contribute to adult osteoporosis." (PMID 39062269, 2024). "In a phase III clinical trial, the subcutaneous administration of antibodies to sclerostin (such as romosozumab, a monoclonal antibody that binds sclerostin) demonstrated efficacy in enhancing BMD compared to the placebo in postmenopausal women with osteoporosis and men with osteoporosis." (PMID 39720253, 2024). "Moreover, the natural WNT antagonist, sclerostin, has become a important target of anti-osteoporosis drugs." (PMID 38744806, 2024). "Importantly, a monoclonal antibody (Romosozumab) that inhibits the Wnt signaling antagonist sclerostin has recently been approved for osteoporosis treatment, as two trials demonstrated that it reduced the rate of vertebral fracture." (PMID 36831232, 2023). "Therefore, sclerostin inhibitors have a rapid and powerful effect on bone mass, and romosozumab was approved by the FDA and EMA in 2019 for treating osteoporosis in postmenopausal women at high risk of fracture." (PMID 38033331, 2023). "At present, the anti-SOST monoclonal antibody is used to treat severe osteoporosis." (PMID 37091847, 2023). "Importantly, the positive correlation between plasma SOST and age also highlights a possible pathophysiological relationship between osteoporosis and AD with ageing." (PMID 37666862, 2023). "Inhibiting the expression of SOST and Dkk-1 and activating the Wnt signaling pathway can effectively increase bone formation and inhibit bone resorption, which is considered an effective method to treat osteoporosis." (PMID 36979418, 2023). "Denosumab, a monoclonal antibody that targets RANKL, and romosozumab, a monoclonal antibody that inhibits sclerostin, have both been approved for the treatment of osteoporosis and have demonstrated significant benefits in increasing bone density and reducing fracture risk." (PMID 37680888, 2023). "This issue raised caution regarding the use of romosozumab, a novel monoclonal antibody for the treatment of osteoporosis that binds and inhibits sclerostin, due to a hypothetical worsening of RA and other autoimmune diseases that involve TNF-dependent inflammation." (PMID 37887030, 2023). "In addition to hormones, cytokines such as receptor activator of nuclear factor-kappa B ligand (RANKL) and sclerostin have also been identified as potential targets for osteoporosis therapy." (PMID 37680888, 2023). "Therefore, blocking the interaction between LRP5/6 and SOST is proposed as an effective treatment for osteoporosis." (PMID 36979418, 2023). "The pivotal role of SOST in aging-related osteoporosis has been elucidated in rodent models." (PMID 37198221, 2023). "As MERTK-RHOA-ROCK signaling interferes with WNT signaling downstream of Sclerostin, activation of MERTK could represent a potential resistance mechanism for Sclerostin-directed therapy in osteoporosis and other bone diseases." (PMID 38203403, 2023). "According to these results, in addition to osteoporosis, sclerostin could contribute to the treatment of obesity." (PMID 35216490, 2022). "Therefore, studies concerning sclerostin can increase our understanding of the pathophysiology and course of treatment for osteoporosis in patients with SCI." (PMID 35742035, 2022). "In summary, studies in vitro and in mice suggest that inhibiting the canonical Wnt/β-catenin signaling pathway, especially through increased expression of its antagonists like sclerostin, is an important factor contributing to glucocorticoid-induced osteoporosis." (PMID 36407318, 2022). "Therefore, further studies are needed to clarify the roles of PGE2 in sclerostin expression in bone metabolic diseases, including osteoporosis." (PMID 35563281, 2022).
osteoporosis (continued). "Additionally, treatment with antibodies against sclerostin in mice prevented glucocorticoid-induced osteoporosis." (PMID 36407318, 2022). "Serum sclerostin was found higher in postmenopausal than premenopausal women, and the administration of selective estrogen receptor modulators (SERMs) for the treatment of osteoporosis reduced serum sclerostin levels." (PMID 35160258, 2022). "A humanized monoclonal sclerostin-neutralizing antibody (Scl-Ab) called romosozumab was approved in 2019 by the Food and Drug Administration (FDA) for treating osteoporosis in patients with a high risk of fracture, following years of clinical trials evaluating the pharmacology, efficacy, and safety." (PMID 35562828, 2022). "These SIK2 inhibitors may replace anti-sclerostin antibodies in the treatment of osteoporosis in the future." (PMID 35563281, 2022). "Hence, discovery of new inhibitors of SOST, particularly for small chemical molecules, is urgently needed for the treatment of cancer bone metastasis and osteoporosis safely." (PMID 36581888, 2022). "Recently, a SOST inhibition agent was introduced as a new osteoporosis therapy." (PMID 36497192, 2022). "It was suggested that sclerostin could be an important endocrine regulatory factor and potential therapeutic target of osteoporosis and sarcopenia in men." (PMID 36456918, 2022). "Circulating sclerostin and irisin levels might involve in pathogenesis of osteoporosis and sarcopenia, which could be novel biomarkers and promising therapeutic targets for osteoporosis and sarcopenia in men." (PMID 36456918, 2022). "Recently, a sclerostin antibody was introduced as a target biomarker to treat osteoporosis." (PMID 35742035, 2022). "The majority of patients with elevated sclerostin also have osteopenia or osteoporosis." (PMID 36506070, 2022). "Sclerostin also functions as the main mediator of bone loss after SCI, and SOST-deficient mice were resistant to cancellous hindlimbs, cortical bone deficits osteoporosis in the sublesional regions of the lower extremities after SCI." (PMID 36378815, 2022). "Notably, the SOST monoclonal antibodies currently used for the treatment of osteoporosis primarily target loop 2 of SOST, which is involved in cardiovascular protection." (PMID 36581888, 2022). "In addition, the aberrant regulation of Wnt inhibitors such as Sclerostin (SOST) and Dickkopf (DKK), which bind to LRP5/6, was found to cause different bone diseases, such as sclerosteosis and osteoporosis." (PMID 36497192, 2022). "Romosozumab is a newly available treatment for osteoporosis acting by sclerostin inhibition." (PMID 34738659, 2022). "The discovery of osteocyte-secreted proteins such as sclerostin has already led to new osteoporosis treatments, and more recently, other molecular osteocytic and nonosteocytic proteins and nanostructures involved in the process of mechanosensation, such as the calcium channel Piezo1, were revealed." (PMID 33738515, 2022). "Sclerostin is certainly involved in the onset of osteoporosis because the administration of anti-sclerostin antibodies (Romosozumab) increased bone formation and decreased bone resorption, which, in turn, markedly increased bone mass in osteoporosis models and patients as previously reported." (PMID 35563281, 2022). "Data regarding clinical factors affecting sclerostin concentration could help with the strategic development of preventative strategies or treatment options for osteoporosis in patients with SCI." (PMID 35742035, 2022). "Sclerostin represents a protein that is almost specifically produced by mechanosensitive osteocytes, which highlights the potential role of osteocytes in the pathogenesis of disuse osteoporosis." (PMID 33738515, 2022). "In the view of the breakthrough that anti-sclerostin becomes a new target for osteoporosis treatment, future studies on the regulatory function of sclerostin on dentin biomineralization may promote the development of dentin repair and pulp regeneration." (PMID 35562828, 2022).